ETS1 (ETS proto-oncogene 1, transcription factor)
Diseases named in the same sentence as ETS1 in open-access papers (continued):
Sharing a sentence is not in itself a finding about the gene and the disease.
tumor (continued). "Transcription factor Ets-1 plays important role in angiogenesis, remodeling of extracellular matrix, and tumor metastasis." (PMID 21439064, 2011). "Despite a significant amount of ETS-1 in the cytoplasm of both primary and advanced tumor cells, the T38-phosphorylated fraction in the nuclear extracts was clearly visible only in the A375M metastatic cell line." (PMID 21711453, 2011). "Pertaining to cancer ETS1 is best known for its role in promoting tumor cell invasiveness, motility and metastasis." (PMID 21445343, 2011). "Ets-1 is the first member of the family implicated in angiogenesis, remodeling of extracellular matrix (ECM), and tumor cell metastasis." (PMID 21439064, 2011). "Positive correlations between OPN intensity and that of PEA3 (r=0.600; P<0.01), Ets1 (r=0.552; P<0.01), Ets2 (r=0.521; P<0.01) were observed in primary tumours." (PMID 21343932, 2011). "In the majority of matched pairs, OPN expression was decreased or unchanged in the liver metastasis compared with the primary tumour, whereas Ets1, Ets2, PEA3, Tcf4 and β-catenin were predominantly increased." (PMID 21343932, 2011). "Several studies support a role for Ets-1 expression in the development of tumor angiogenesis in many different types of human cancer." (PMID 20454645, 2010). "Traditionally, Ets-1 is thought to function as a transcriptional activator and its high expression in endothelial and stromal cells correlates with tumour cell invasiveness and unfavourable outcome in ovarian and breast cancer." (PMID 21042593, 2010). "Subsequent treatment of these cells with H2O2 increased Ets-1 expression in a dose-dependent manner, suggesting that this transcription factor is highly responsive to tumour-derived signals." (PMID 21042593, 2010). "Transcriptional activation of ETS1 by WT1 has been reported in tumour vascularisation via regulation of endothelial cell proliferation and migration." (PMID 20842112, 2010). "To determine the precise biological role of Ets1 in tumor formation and progression, we developed a transgenic mouse model that allows us to induce the expression of an Ets1 transgene in a spatially and temporally-restricted manner." (PMID 19142229, 2009). "Ets1 is an oncogene that functions as a transcription factor and regulates the activity of many genes potentially important for tumor initiation and progression." (PMID 19142229, 2009). "We observed specific cellular immunostaining for ETS-1 in the retinal site surrounding the optic nerve at the point of tumor development at P25." (PMID 18958307, 2008). "This is consistent with recent data obtained from tumor cell lines where RA induced the synthesis of Ets-1 and STAT-6, transcription factors that are involved in Th2 differentiation." (PMID 17118196, 2006). "ETS-1 staining was predominantly seen in the cytoplasm of tumour cells in positive cases, although a mixed nuclear and cytoplasmic expression pattern was also observed." (PMID 16189525, 2005). "A total of 125 cases had sufficient tumour tissue in the TMA sections to be evaluated for ETS-1 staining in tumour cells; and 26 cases (21%) were regarded to be negative (SI⩽1)." (PMID 16189525, 2005). "Using immunohistochemistry, Ets-1 was found predominantly in tumour cells, but was also detected in some stromal cells surrounding tumour islands." (PMID 15365563, 2004). "In this investigation, we found the Ets-1 protein to be present in both tumour and stromal cells, especially when the latter surrounded tumour islands." (PMID 15365563, 2004). "The clinical potential of ETS-1 in tumor immunotherapy is vast." (PMID 40181983, 2025). "In addition to its direct effects on immune cells, ETS-1 influences the tumor microenvironment by regulating the extracellular matrix (ECM) composition and structure." (PMID 40181983, 2025). "WTAP accelerates tumor growth in HCC xenograft models by regulating the m6A modification of ETS1." (PMID 40568348, 2025).
tumor (continued). "ETS1 has been shown to regulate multiple pathways involved in extracellular matrix remodeling, angiogenesis, and immune cell recruitment, thereby promoting tumor invasion and metastasis." (PMID 40948762, 2025). "To determine whether ETS1 overexpression impairs CD8+ T cell-mediated tumor killing, we established an ex vivo co-culture assay." (PMID 40777467, 2025). "In addition, ETS1 can reduce the mRNA levels of Twist1, a gene involved in tumor cell motility and dissemination, thereby decreasing invasion and increasing cell growth to mitigate lung tumor metastasis." (PMID 40181983, 2025). "Additionally, ETS-1 plays a crucial role in shaping the tumor immune microenvironment by regulating the expression of immunosuppressive factors, such as TGF-β." (PMID 40181983, 2025). "Therefore, a detailed investigation into the roles of key molecules such as ETS-1 in tumor immunity is of great significance for developing novel immunotherapeutic approaches." (PMID 40181983, 2025). "ETS-1 promotes tumor advancement not only by regulating tumor cell proliferation, migration, and invasion but also by contributing to immune escape mechanisms through modulation of immune cell infiltration, activation, and immune checkpoint molecule expression within the tumor microenvironment." (PMID 40181983, 2025). "Moreover, ETS-1 also influences the tumor immune microenvironment by regulating immune cell functions and interacting with other signaling molecules in several malignancies, making it an important target for cancer diagnosis, prognosis, and therapy." (PMID 41155227, 2025). "The potential interaction between ETS1 and ZMYND11 in the context of THCA could provide a more complex regulatory mechanism underlying tumor progression." (PMID 40938895, 2025). "It is interesting to notice that, in our series of nonmalignant thyroid samples, if positive, nonmalignant thyroid cells of the follicles close to the tumor showed intense nuclear staining, while the intensity of ETS1 IHC staining of NMT declined along with the distance from the tumor." (PMID 39941022, 2025). "These integrated results establish the circPPFIA2/miR-646/miR-1200/ETS1 axis as a central oncogenic driver in PCa, wherein circPPFIA2 acts as a molecular sponge to liberate ETS1 from miRNA-mediated repression, unleashing its tumor-promoting transcriptional programs." (PMID 41360764, 2025). "ETS-1 up-regulates the expression of MMPs, which not only helps tumor cells break through the matrix barrier and infiltrate and metastasize to surrounding tissues but also affects the infiltration and distribution of immune cells by changing the physical structure of the tumor microenvironment." (PMID 40181983, 2025). "Consequently, the pivotal role of ETS-1 in tumor immune evasion highlights its potential as a promising target for immunotherapy." (PMID 40181983, 2025). "This evidence further substantiated the opposite effects of EFNA4 and ETS1 in the context of tumour immunity, playing an important role in immune cell-related pathways, and suggesting that they may affect the progression of GC through T cell exhaustion." (PMID 41162582, 2025). "Therefore, understanding the mechanisms of ETS-1 in cancer is of great significance for developing novel anti-tumor strategies." (PMID 40181983, 2025). "While p16 methylation alone may not directly influence clinical outcomes, its interaction with ETS1 could still play a role in tumor advancement and may contribute to more aggressive tumor behavior." (PMID 40722658, 2025). "In EGC, the expression level of ETS1 in tumour cells in state 1 was high and decreased over time." (PMID 41162582, 2025). "Taken together, we have demonstrated that the expression of EFNA4 and ETS1 may influence the differentiation and characteristics of tumour cells, thereby affecting the progression of GC." (PMID 41162582, 2025).
tumor (continued). "Evaluating the differential expression of ETS-1 across cancer subtypes may facilitate the identification of novel molecular markers for tumor diagnosis and prognosis." (PMID 40181983, 2025). "Furthermore, ETS-1 promotes tumor immune escape by directly regulating the expression of multiple immune checkpoint molecules." (PMID 40181983, 2025). "Inhibiting ETS-1 expression or function may help disrupt the immune escape process, potentially restoring the anti-tumor activity of the immune system." (PMID 40181983, 2025). "This is noteworthy, as ETS1 has not been previously implicated in the regulation of anti-tumor immune response." (PMID 40777467, 2025). "ETS1 induces aggressive tumor cell generation, resistance of tumor cells, and angiogenesis." (PMID 38287102, 2024). "This understanding may ultimately contribute to the development of targeted treatments aimed at modulating Ets-1 activity to inhibit tumor progression." (PMID 39468027, 2024). "Through a series of functionalistic experiments, including CCK-8, tumor sphere formation, colony formation and transwell assays, we observed that the knockdown of ETS1 significantly suppressed the capability of OSCC cells to proliferate, form tumor spheres, migrate and invade." (PMID 38993570, 2024). "Importantly, interrogation of tumor gene expression profiles from five independent datasets showed a positive correlation of ETS1 and TNS3 expression and association of high TNS3 expression with a poorer overall survival probability." (PMID 38187702, 2023). "Indeed, overexpression of GATA6-AS1 inhibited PDAC cells proliferation, migration, invasion, and EMT, while further overexpression of ETS1 led to a significant rescue in tumor aggressive phenotype in both normoxic and hypoxic settings." (PMID 38057853, 2023). "CpG islands located at RIIAD1, ENPP2, ESPN, and ETS1, were hyper-methylated in BC tumor." (PMID 38082340, 2023). "We next examined whether overexpression of ETS1 could restore GATA6-AS1-inhibited tumor aggressive phenotype under hypoxic conditions." (PMID 38057853, 2023). "Functionally, overexpression of ETS1 could rescue these tumor-inhibitive phenotypes induced by GATA6-AS1 overexpression under normoxic or hypoxic conditions." (PMID 38057853, 2023). "Specifically, SRC kinase-mediated NF-κB activation is required for CTGF-induced Glut3 expression and the aggressive phenotypes of TNBC, while SRC-mediated ETS1 phosphorylation can stabilize ETS1 and promote anchorage-independent growth in vitro and tumor growth in vivo." (PMID 36581908, 2022). "ETS1 may be a reliable biomarker for tumor prognosis and a viable prospective therapeutic target for human cancer immunotherapy (e.g., KIRP, MESO, BLCA, KIRC, and THYM)." (PMID 35463077, 2022). "Additionally, Ets1 knockdown impairs tumor growth in breast and melanoma cancer and the progression of proliferative, metastatic, and invasive gastric cancer." (PMID 36305724, 2022). "ETS-1 blockade enhances the anti-tumor capacity of sorafenib by withdrawing PXR activation." (PMID 35002522, 2022). "Therefore, we concluded that ETS1 enhanced the transport of tumor cell-derived exosomes to omental resident macrophages through exosomal laminins interaction with macrophage integrin αvβ5, laying the foundation for the establishment a pre-metastatic niche." (PMID 36477408, 2022). "However, anti-PD-L1 treatment resulted in upregulation or downregulation of numerous genes in CD45+ tumor-infiltrating immune cells in TCh3 tumors, including Cd3d, Cd3e, Cd3g, Cd8a, Cd8b1, Nkg7, Ccl5, Ets1, Icos, Cxcr6, Pdcd1, Lag3, Prf1, and Gzmb (right)." (PMID 35366939, 2022). "To determine the role of ETS1 in tumor progression in vivo, we used SGC7901-H cells to establish a stable ETS1-silenced cell line by lentiviral-mediated shRNA, and then the ETS1-silenced SGC7901-H cells were intraperitoneally injected into BALB/c nude mice, followed by the bioluminescence imaging." (PMID 33407516, 2021).
tumor (continued). "Upon receiving the microenvironmental stimuli, ETS1 expression increases and it translocate to the nucleus, where it transcriptionally activates different MMP genes as well as regulates different genes associated with metabolic reprogramming of tumor cells." (PMID 34136678, 2021). "Some evidence indicates that ETS-1 is closely related to the progression of a variety of tumors, including breast cancer and liver cancer, and its high expression is positively correlated with the degree of tumor malignancy." (PMID 34858853, 2021). "Our results identified ETS1 as a key factor regulating tumor angiogenesis, and suggested that TGFβ inhibition may suppress the vascular abnormality driven by ETS1." (PMID 34867089, 2021). "Taken together, these results indicate that targeting TGFβ signaling, the upstream of ETS1, could suppress tumor angiogenesis and downregulate vascular abnormality associated genes." (PMID 34867089, 2021). "We next set out whether TGFβ signaling, which is the upstream of ETS1 signaling, affects the tumor angiogenesis and vascular abnormality." (PMID 34867089, 2021). "Notably, neutralizing TGFβ antibody treatment attenuated tumor conditioned medium induced upregulation of ETS1 expression in bEND.3." (PMID 34867089, 2021). "If MBs with REST elevation do indeed mimic endothelial cells, we reasoned that transcription factors directing endothelial specification such as ETS1 may also be expressed in tumor cells." (PMID 33469989, 2021). "MMP genes are mostly regulated by the ETS1 oncogenic transcription factor in invasive tumor cells." (PMID 34136678, 2021). "In vitro angiogenesis assays showed that a reduction in ETS1 expression in DAOY‐R caused a significant decline in tube formation, as well as a decrease in tumor endothelial cell colocalization at the tubes, confirming the involvement of ETS1 in this process under conditions of REST elevation." (PMID 33469989, 2021). "Notably, SOX4 and ETS1, which were identified as activated transcription factors in ECs in the tumor core, were also upregulated in ECs in the tumor core." (PMID 34228647, 2021). "Furthermore, the cross-talk of ETS1 with microenvironment makes it an essential factor for tumor metastasis, serving as a candidate therapeutic target." (PMID 31894857, 2020). "Collectively, these results suggest anti-tumorigenic functions of ETS1 in a tumor-dependent manner." (PMID 32477936, 2020). "Because Ets1 could affect extracellular matrix (ECM) degradation which was the premise of tumor cell metastasis." (PMID 32984354, 2020). "To confirm whether ETS1 has anti-oncogenic function in general or in specific types of tumor, we extended previous analysis to other cancers as well." (PMID 32477936, 2020). "Key findings from our studies have identified E2F1, FOXM1, and ETS1 as coding gene/s axes that are overexpressed and may show strong involvement in tumor development in almost all cancer types." (PMID 30809433, 2019). "We also determined the protein level of ETS1 in tumor and normal tissues (n = 3 in each group)." (PMID 31889958, 2019). "Indeed, a recent pan cancer survey of EMT markers across the TCGA has revealed ETS1 to be one of the highest ranked TF which showed significant EMT correlations within multiple tumor types that span various histological or cellular backgrounds." (PMID 31306413, 2019). "ETS1 transcription factor has been reported to play a role in tumor vascularization and invasion." (PMID 31578247, 2019). "Here we have comprehensively examined ETS1 in HNSCC, where we find ETS1 to be specifically enriched in expression across cell lines, human tumors and PDXs representing the mesenchymal subtype and associated with poor tumor outcome." (PMID 31306413, 2019).
tumor (continued). "The third miRNA, mir-125b may have oncogenic or tumor-suppressive effects depending on the cell context, but has been shown to downregulate expression of pro-proliferative genes such as ETS1." (PMID 31208318, 2019). "It was also observed that the down-regulation of ETS1 led to the inhibition of tumor growth." (PMID 29950928, 2018). "ETS1 is a TF regulates genes involved in stem cell development, tumor genesis and metastasis." (PMID 29950928, 2018). "Signaling of ETS1/P38 has been proposed to play an important role in the development of tumor." (PMID 29950928, 2018). "Analysis of fresh tumour tissue from primary or metastatic sites by immunoblotting suggested that Usp9x positivity was more common in metastatic (8/9) than primary tumour (3/9) and correlated with higher Ets-1 (or its isoform) levels in most Usp9x-expressing tumours." (PMID 28198367, 2017). "Moreover, ETS1 was shown to contribute to tumor proliferation and invasion by acting in both fibroblasts and neoplastic cells in tumor stroma." (PMID 29340052, 2017). "Prior studies have suggested induction of ETS‐1 in response to oxidative stress; implying that the tumor microenvironment may drive increased ETS‐1 expression, which enhances the ability of these cells to promote metastasis." (PMID 28236660, 2017). "Additionally, ETS-1 is a molecular target of miR-144-3p, and silencing ETS-1 expression inhibited FaDu and Hep2 cell invasion and migration as well as reduced Hep2 xenograft tumor volume." (PMID 26826553, 2016). "Ets1 also induces expression of the epithelial-mesenchymal transition (EMT) transcription factor Zeb1, and thereby links Ras mutation to EMT, which is thought to drive tumor invasion." (PMID 25880398, 2015). "Ets-1 mainly exhibited a nuclear and cytoplasmic immunostaining in tumor cells." (PMID 25264483, 2014). "Finally from these disease modules we identify their upstream transcription factors E2F4, AR and ETS1 as potential key regulators in tumour progression." (PMID 24523864, 2014). "In addition to promoting MDR in cancer cells, ETS1 is also likely to play a role in tumor progression." (PMID 24602286, 2014). "Thus, a signal loop involving Ets-1 and αvβ6 probably exists to play a key role in tumor cellular growth and migration." (PMID 25264483, 2014). "Furthermore, our findings suggest that PARP-1 inhibitors would be useful in a new therapeutic strategy that specifically targets Ets-1-expressing tumours." (PMID 23405229, 2013). "Ets1 was originally cloned from an oncogenic retrovirus and has been shown to be over-expressed in many human tumors, where high levels of expression are correlated with tumor aggression and invasion." (PMID 24337118, 2013). "Specifically, Ets1 has been shown to play a role in cSCC tumor development and progression." (PMID 23646287, 2013). "Given the established tumor suppressive role for Notch signaling in skin tumorigenesis, the demonstrated ability of Ets1 to interfere with this signaling pathway may be important in mediating its pro-tumorigenic activities." (PMID 24337118, 2013). "Although Ets1, acting alone, may activate genes to stimulate cellular proliferation, the continued estradiol-dependence of tumor growth suggests that the cooperative interaction between Ets1 and ERα is responsible." (PMID 23874775, 2013). "We show that Ets1 expression increases cellular proliferation, colony formation, migration and invasion in vitro and increases 17β-estradiol-dependent tumor growth in vivo." (PMID 23874775, 2013). "Furthermore, NO activation of Ets-1 resulted in increased expression and activity of proteases critical for tumor metastasis, MMPs and CTSB, and resulted in increased cancer cell invasion and proliferation." (PMID 22971289, 2012). "Ets-1 expression is upregulated in endothelial cells of neo-vessels during tumor angiogenesis." (PMID 21439064, 2011).